IL13 (interleukin 13)
Diseases named in the same sentence as IL13 in open-access papers (continued):
Sharing a sentence is not in itself a finding about the gene and the disease.
tumor (continued). "Following short-term restimulation of colonic ILC subsets isolated from tumour-bearing CAC mice with phorbol myristate acetate and ionomycin we observed significant increases in TNF-α (ILC1), IL-5 and IL-13 (ILC2) and IL-17 (ILC3) production in tumour-bearing mice." (PMID 33535624, 2021). "We observed significant negative correlations between CD68+ macrophage infiltrations in the tumor tissue and the concentrations of the cytokines eotaxin, IFN-γ, IL-1β, IL-2, IL-10, IL-13, IL-16, VEGF and factor score of component 2 (“Inflammatory Cluster”) in the CSF." (PMID 34654395, 2021). "Following differentiation, Th2 cells can produce IL-4, IL-5, IL-10, IL-13, and IL-17, not all of which are beneficial in cancer and contribute to tumor growth and metastasis." (PMID 35087869, 2021). "The association with TNM in CRC resulted from IL-13 decrease along with increasing TNM in adjacent tissue (ρ = −0.42, p = 0.093) rather than its increase in tumor (ρ = 0.20, p = 0.436)." (PMID 32512917, 2020). "The cells of tumor and TME secrete CCL2 and macrophage colony-stimulating factor (M-CSF) and attract a large number of inflammatory monocytes to tumor sites where they differentiate into TAMs due to secretion of IL4, IL10, and IL13." (PMID 32582698, 2020). "On the other hand, IL-13 when bound to IL-13Rα2 in tumor cells does not recruit another chain but mediates signaling through a different pathway." (PMID 32443847, 2020). "Also, IL13 levels were higher in the plasma of patients with HCC with vascular invasion, which is a known indicator of metastatic tumor spread in HCC (p=0.01)." (PMID 31933479, 2020). "As we have shown, this can result in significant IL-13 release, which is a key mediator of tissue repair, but may be detrimental in this setting through IL-13R/STAT6 signaling on tumor cells." (PMID 32508830, 2020). "In addition, tumor tissue from ESCC patients had significantly lower IL13Ra1 and IL13 expression as compared to GC patients." (PMID 32512917, 2020). "Moreover, widespread cell death triggers efferocytosis-induced wound-healing cytokines, such as IL-4, IL-10, IL-13, and transforming growth factor β (TGF-β), in the TME to further promote metastatic tumor progression." (PMID 32346605, 2020). "The differences in both IL13 and IL13Ra1 transcripts between adjacent and tumor tissue were non-significant." (PMID 32512917, 2020). "Considering that tumor cells that have undergone EMT are more likely to metastasize, we next sought to measure the migratory properties of the immortalized MCF10A cells exposed to M0 and M(IL‐4 + IL‐13) THP‐1 CM." (PMID 32713010, 2020). "This shift could be significant in CRC because while IL-13 is important in tissue repair, it can also promote CRC tumor growth and metastasis, and can inhibit anti-tumor immunity by promoting a Th2-type microenvironment." (PMID 32508830, 2020). "In this scenario, the IL-33-mediated activation of ILC2 cells might control the development of metastasis by promoting tumor immune-surveillance through eosinophil infiltration due to ILC2-derived IL-5 and IL-13." (PMID 33138017, 2020). "Suppressive immune cells in the TME often preferably express pro-tumor Th2 secreted cytokines, such as IL-4 and IL-13, rather than anti-tumor Th1 (e.g., IL-2 production), or secreted cytokines like IFN-γ and tumor necrosis factor-β (TNF-β)." (PMID 32843053, 2020). "Cytokines released from tumor-residing cells including tumor cell–derived IL-4, IL-10, CCL2, CCL3, CCL4, and CSF1; Treg-derived IL-10; B cell–produced immunoglobulins; Th2-derived IL-4 and IL-13; and MSC-derived MFG-E8 promote the polarization into a protumor phenotype." (PMID 31256327, 2020). "When we further analyzed the tumor tissue for pro- and anti-inflammatory markers, we observed a trend towards more inflammation, together with lower expression of markers typical for M(IL4+IL13)-polarized macrophages." (PMID 31178956, 2019).
tumor (continued). "While in vitro studies on IL-13 in various cancer model systems are abundant, no clinical or in vivo mouse data link IL-13 directly to pro-tumor or anti-tumor effects to date." (PMID 30759882, 2019). "Mast cells release IL13, which activates PSC, further promoting tumor growth." (PMID 31921628, 2019). "Contrary, M2 TAM are activated with transforming growth factor beta (TGF-β), interleukin 4(IL-4) and interleukin 13 (IL-13) to release a set of growth factors: VEGF, epidermal growth factor (EGF), and fibroblast growth factor (FGF); thus promoting angiogenesis and tumor growth." (PMID 30680411, 2019). "SI-CLP was shown to induce the secretion of IL-1β, IL-6, IL-12, and IL-13 in PMA-treated THP-1 cells, suggesting that it may serve as a regulator of inflammation and in the tumor microenvironment." (PMID 32038607, 2019). "In addition, several cytokines, such as IL-4, IL-13, RANKL, and TNF-α, seem to play an important role in the process of macrophage fusion, myoblast fusion and even in tumour-hybrid formation." (PMID 31266502, 2019). "Likewise, cytokines such as IL-1β, IL-4, IL-13 and TNF-α facilitate the cell fusion process that results in increased tumour-hybrid formation." (PMID 31266502, 2019). "In this model, it was shown that ILC2s mediate antitumor activity either by producing cytokines relevant in tumor control (IL-5, IL-13, and GM-CSF) or by producing CXCR2 ligands (CXCL1 and CXCL2), which could induce the apoptosis of CXCR2+ tumor cells." (PMID 32063901, 2019). "Indeed, Schiechl and colleagues provide strong evidence to validate this preventative approach as blocking IL-13 or depleting NKT cells reduced inflammation, tumor size and tumor number." (PMID 30460209, 2018). "Neoadjuvant chemotherapy seemed to result in a relocation of Th1-committed CD4+ T cells from blood, presumably to the tumour, indicated by shifts in the methylation patterns, whereas no such shifts were seen for lineages corresponding to IL13, IL17A and FOXP3." (PMID 30075815, 2018). "In a first phase (elimination phase), the stimulated immune system produced many costimulating cytokines (TNFα, IL1, IFNα, TLR, ICAM1, IL2, IL12, IFNγ,) and less inhibitors (IL10, IL4, IL13, PD1/PD-L1, prostaglandins, LAG-3, TGFβ) resulting in efficient tumor cell killing." (PMID 29492219, 2018). "Since IL-13 is a secretory cytokine present in systemic circulation, the IL-13 in GBM tumor micro-environment may be sufficient enough to trigger AP-1 signaling." (PMID 30572904, 2018). "A similar mechanism may underlie the dNKT-cell suppression of immunity to a B lymphoma where increased levels of IL-13, TGF-β, and myeloid-derived suppressor cells correlated with enhanced tumor growth." (PMID 29375569, 2017). "In this study, we noticed that anti-IL-25 treatment only reduced the IL-4-producing Th2 cells in the tumor microenvironment, but did not affect the expression of IL-5 and IL-13." (PMID 27909985, 2017). "Similarly, disruption of this tumour immunosuppressive axis by specifically blocking PGD2, IL-13 and NKp30 partially restores ILC2 and M-MDSC levels and results in increased survival." (PMID 28928446, 2017). "We screened the expression and distribution of a panel of immune markers in ESCC primary tumor samples firstly, and found that the distribution of CD68 and interleukin 13 (IL-13) could distinguish between good and poor prognosis." (PMID 26771842, 2016). "Mice lacking IL-13 were significantly more susceptible to DMBA-induced carcinogenesis and developed both more and bigger tumours than WT mice." (PMID 27357235, 2016). "Further, a model based on tumor stroma densities of CD68 and IL-13 was constructed and it could significantly classify patients with poor or good prognosis." (PMID 26771842, 2016). "Notably, both of the representative Th2 cytokine genes Il4 and Il13 and the representative Th1 cytokine gene Ifng were significantly upregulated in NM11-shsST2 tumours." (PMID 27882929, 2016).
tumor (continued). "Curiously, when tumour-protective skin-resident IELs are activated by stressed ECs in the LSS response, a dominant Th2-biased downstream response is triggered with large amounts of interleukin (IL)-13 and IgE being produced." (PMID 27357235, 2016). "Survival analyses assessed by Kaplan-Meier plots and log-rank tests demonstrated that densities of CD68 and interleukin 13 (IL-13) in tumor stroma were positively correlated with the overall survival of ESCC patients after operation (p < 0.01 for CD68, p < 0.001 for IL-13)." (PMID 26771842, 2016). "Results demonstrated that IL-13 could be expressed by CD3, CD4, CD8, CD56, CD68 and CD20 positive cell respectively in ESCC tumor tissue." (PMID 26771842, 2016). "Moreover, some studies found that macrophage treated with IL-4 or IL-13 (alternatively activated macrophage) could express high levels of dectin-121, suggesting that these immune regulatory cytokines might also influence tumor cell dectin-1 expression, like a tumor-host cytokine interaction." (PMID 27600310, 2016). "Freshly isolated monocytes were differentiated into MDM with M-CSF before polarization into M1 using IFN-γ and LPS or into M2 macrophages by IL-4 and IL-13, or were co-cultured with NCI-H460 or MCF-7 tumour cells to better mimic a realistic situation of macrophage polarization by tumours." (PMID 25902944, 2015). "Macrophages are known to produce CCL2 in response to IL-4/IL-13 stimulation, and the increase in CCL2 production we detected during lung tumorigenesis indicates that there is a Th2 response occurring in lungs during tumor formation." (PMID 25505466, 2014). "Accordingly, the authors suggested that tumor expression of CD1d might shift the NKT cell response toward a Th2 skewed anti-inflammatory reaction, which produces more IL-13, TGF-β, and inhibition of CTL and NK cell activity." (PMID 25389427, 2014). "Many epithelial cancers express receptors for type 2 mediators such as IL-4 and IL-13, allowing for a direct effect on tumor growth, death, and proliferation that is independent of their effect on immunocytes." (PMID 25101088, 2014). "IL2-PE, a immunotoxin known to exert its cytotoxicity through binding to IL-2 receptor γ chain was not cytotoxic to IL-13Rα2 positive tumor cells confirming that IL-13-PE-mediated cytotoxicity is IL-13Rα2 specific." (PMID 23421960, 2013). "Considering that IL-4/IL-13 and IFN-γ/IL-12 counter regulate each other, our finding that IL-13 is protective is in line with the previous observation that IFN-γ and IL-12 can be tumor-promoting in DMBA/TPA carcinogenesis." (PMID 24403255, 2013). "In vivo studies reveal that immunoliposomes conjugated with different ligands to target specific tumor antigens, for example, VCAM-1, interleukin-13, and EGFR, may be of important clinical significance as a novel treatment for cancer." (PMID 24175095, 2013). "This IL-13-PE regimen significantly increased survival in the tumor bearing mice (P value 0.002) with no signs of toxicity." (PMID 23421960, 2013). "The MDSCs, however, may be particularly sensitive to IL-13-PE treatment since IL-13Rα2 has been shown to express on some populations of these myeloid cells in order to induce TGF-β1 secretion and promote tumor immune evasion." (PMID 23421960, 2013). "This may be due to a direct cytotoxic effect of IL-13-PE on MDSCs, since some of these myeloid cells are known to express IL-13Rα2 in order to induce TGF-β1 secretion and promote tumor immune evasion." (PMID 23421960, 2013). "Indeed, we demonstrate that pre-treatment of tumor cell lines in vitro with TSA enhanced their sensitivity to IL-13-PE and made IL-13Rα2-negative cell lines extremely sensitive to IL-13-PE." (PMID 21477288, 2011). "Interestingly, M2 macrophages (derived from direct tumor cell contact and IL4, IL10 and IL13 exposure) drive a Th2 response resulting in increased expression of anti-inflammatory cytokines and down-regulation of pro-inflammatory mediators." (PMID 21629653, 2011).
tumor (continued). "The tumor-infiltrating T cells produce high levels of type 2 cytokines, in particular IL-13 (but not IL-10)." (PMID 21281484, 2011). "Neither TSA nor IL-13-PE alone affected the tumor growth, but when combined, a dramatic inhibition of tumor growth was observed." (PMID 21477288, 2011). "However, IL-13 can also inhibit the IFN-γ secretion and CD8+ cytotoxic T lymphocyte (CTL) activity and compromise the anti-tumour immunity response." (PMID 20049171, 2009). "Unlike IL-4/IL-13 polarized macrophages, xenoline-polarized TAMs exhibit a broader spectrum of transcriptional and functional states that more closely mirror the complexity of the tumor microenvironment." (PMID 40386422, 2025). "The M2 phenotypes are, on the other hand, stimulated by IL-4 and IL-13 to produce and secrete growth factors such as VEGF and TGF-β, MMPs and other cytokines such as IL-10, IL-13 and IL-4, and in that way contribute to increased proliferation of tumor cells and angiogenesis in the TME." (PMID 40376304, 2025). "However, Th22 cells also showed enhanced capacity to produce IL-22 and IL-13 in EOCRC, which could promote aggressive tumor behavior and shape an immunosuppressive environment favorable to tumor survival and growth." (PMID 41425582, 2025). "For instance, the generation of IL-13 by ILC2s could contribute to negative outcomes in some cancers, while in others, releasing IL-5 enhances anti-tumor responses." (PMID 40497988, 2025). "CD4+ T helper cells have a dual role: Th1 cells support antitumor responses and can directly kill tumor cells through cytokine release (IFN-γ and TNF-α), while Th2 cells promote tumor progression by secreting anti-inflammatory mediators, such as IL-4 and IL-13, that suppress immune activity." (PMID 41230456, 2025). "IL-13Rα2 does bind to IL-13 more readily than IL-13Rα1 and it is therefore hypothesized that GBM tumors potentially use IL-13Rα2 expression to bind up available IL-13 and prevent immune responses to the tumor cells by stimulating TGF-β production." (PMID 39329751, 2024). "HCH could reverse the pathological lung tissue into approximately normal, the protein expression of Ki-67, VEGF and SMC3 were all reduced, the ROS level was reduced andSOD level was increased, the levels of IL-1β, IL-8, IL-13 and TNF-α were all reduced, the weights of tumor were reduced." (PMID 39211045, 2024). "Additionally, recent studies have identified that protein tyrosine phosphatase-1B inhibitors inhibit IL13 signal transduction, attenuating the invasive and migratory capabilities of IL13Rα2-positive GBM tumor cells, showing promising therapeutic potential in animal experiments." (PMID 38201655, 2024). "These apparently contradictory results may be explained by diverse IL-13 activity in different tumors and the fact that earlier studies investigated tumor cell lines rather than primary tumor cells." (PMID 38003396, 2023). "Type II NKT cells can induce TGF-β secretion from MDSCs by producing IL-13, and blocking IL-13 or TGF-β.Eliminating NKT or myeloid cells may interrupt this immunosuppressive circuit and uncover immune surveillance to prevent tumor recurrence." (PMID 37857728, 2023). "Furthermore, the M2-polarizing factors G-CSF and IL-13 were shown by ELISA to be elevated in tumor-bearing MDX mice as compared with non-tumor-bearing MDX mice." (PMID 37628775, 2023). "In addition, a negative correlation between IL-13 secretion and largest ultrasound height was detected in 1,4-dihydroxy quininib treated tumours." (PMID 36698840, 2022). "Ddx5 was increased in the whole skin lesions of MC903- or IMQ-treated Cd93–/– mice compared with their wild-type counterparts, along with fewer plaques on the ears or dorsal skin and reduced expression of Il4, Il13, Ccl11, Ccl17 and Ccl22 or Cxcl1, Cxcl2, Ccl20, Il23, Il17a and Il36γ." (PMID 36271146, 2022).
tumor (continued). "However, in advanced tumors, anti-inflammatory mediators released in the TME, such as CSF-1, CCL2, IL13, IL4, IL10, and prostaglandin E2 (PGE2), can revert the anti-tumor program and favor a switch of TAM into an M2 phenotype with pro-tumor and immunosuppressive functions." (PMID 35163420, 2022). "Moreover, tumor-recruited Lyve-1+ lymphatic progenitors in vivo expressed all Th2 receptors as well as corresponding ligands, including IL-4 and IL-13, which were absent in BM cells." (PMID 35442077, 2022). "In serum of CT26 tumor-bearing mice, there was extensive overlap with the factors detected in CT26-conditioned media: following mediators identified in conditioned media showed at least a 1.2-fold increase in CT26 tumor-bearing mice: IL-1α, IL-2, IL-13, CCL2/5/19, LIX, CX3CL1, CXCL1/2/10 and CCL19." (PMID 35962398, 2022). "However, our results notably showed that the probiotic group had also a higher level of serum IL-13 compared with the model group; IL-13 is another pleiotropic cytokine involved in negative regulation of anti-tumor immunity." (PMID 36615662, 2022). "For example, immunosuppressive ILC2 may release IL-13 to stimulate the development of immunosuppressive myeloid–derived suppressor cells, whereas inflammatory ILC2 produce IL-5 to enhance the cytotoxic activity of eosinophils to suppress tumor progression." (PMID 33427206, 2021). "However, the IL13–Pseudomonas exotoxin was not distributed widely enough to reach the entire MRI-defined tumor volume in any patient." (PMID 34771443, 2021). "Necrosed tumor cells may contribute to an inflamed TME and also proinflammatory cytokines released by CSCs, such as IL-6, IL-8, IL-10, and IL-13 can contribute to maintaining an inflammatory and suppressive TME representing the “niche” sustaining cellular stemness." (PMID 33494389, 2021). "CD213A2 has been shown to bind to interleukin-13 (IL-13) and activate its immunomodulatory function; however, no direct tumor-related role has been found, so further study of CD213A2 and its effects on HCC, including through methylation and immunity, is warranted." (PMID 34458266, 2021). "Interestingly, TAMs can acquire different functional phenotypes depending on TME signals; they are capable of having either the classical anti-tumor M1 type in response to IFN-γ or lipopolysaccharide or the alternative pro-tumor M2 type by IL-4, IL-10, IL-13, TGF-β and lactic acid." (PMID 33129234, 2021). "In contrast, upon exposure to IL-4, IL-10, and IL-13, transforming growth factor beta 1 (TGFβ1), and prostaglandin E2 (PGE2), macrophages can undergo M2 activation, which is characterized by tissue repair, matrix remodeling, and tumor promotion, and mirrors those of Th2 responses." (PMID 34300195, 2021). "An increased percentage of IL-13-expressing intratumoral ILC2 was observed in parallel with the recruitment of immune-suppressive TAMs, IL-10-expressing DCs and MDSCs in an IL-33-treated breast cancer model with accelerated tumor progression and lung/liver metastases." (PMID 34884995, 2021). "While Th2 and Th17 cells may promote tumor growth through expression of immunosuppressive cytokines including IL-4, IL-5, IL-13, and IL-17A, although the contribution of these cells to the tumor immune landscape is not completely clear." (PMID 34202979, 2021). "Thus, JAK3 promotes survival and proliferation of malignant T cells and expression of proto-oncogenes/oncomiRs and cytokines (IL-5, IL-9, IL-13, IL-17F and LTA), some of which are growth factor to malignant T cells while others modulate the tumour micro-environment (TME) and anti-cancer immunity." (PMID 33466582, 2021). "Moreover, through the secretion of IL-13, ILC2 have been shown to promote DC migration and cytotoxic T cell activation, which might support anti-tumor immunity." (PMID 33371444, 2020).